SETBP1 (SET binding protein 1)
Synonyms: SEB; KIAA0437; MRD29
Tractability: PROTAC: ubiquitination databases record sites on it.
Gene: Protein-coding gene on chromosome 18 (44,680,173 to 45,068,510, forward strand). Ensembl gene ENSG00000152217.
Subcellular location: Nucleus
Subcellular location (Human Protein Atlas): Nucleoplasm; Cytosol; Nuclear bodies; Nuclear membrane
Gene Ontology:
Molecular function: protein binding; histone H3K4 methyltransferase activity; DNA binding
Biological process: regulation of DNA-templated transcription; chromatin remodeling
Cellular component: nuclear body; nuclear membrane; nucleoplasm; nucleus
Genetic constraint (gnomAD): Loss-of-function variants: 8 observed, 100.95 expected, observed/expected ratio (o/e) 0.0792, 90% interval 0.046 to 0.14. The upper end of that interval is the gene's LOEUF score, 0.14, which puts it in group 1 of 6, group 1 being the genes least tolerant of losing a copy. Missense variants: 1,820 observed, 2,050.1 expected, observed/expected ratio (o/e) 0.89, 90% interval 0.85 to 0.92. Synonymous variants: 800 observed, 794.9 expected, observed/expected ratio (o/e) 1.01, 90% interval 0.95 to 1.07.
Gene-disease validity (ClinGen):
ClinGen rates the evidence that SETBP1 causes each of these diseases.
complex neurodevelopmental disorder (autosomal dominant): Definitive. A disorder that involves more than one phenotype associated with the central nervous system, including but not limited to intellectual disability, autism, and seizures (epilepsy).
Schinzel-Giedion syndrome (autosomal dominant): Definitive. Schinzel-Giedion syndrome (SGS) is an ectodermal dysplasia syndrome chiefly characterized by a distinctive facial dysmorphism, hydronephrosis, severe developmental delay, typical skeletal malformations, and genital and cardiac anomalies.
Cancer hallmarks: proliferative signalling (promotes); invasion and metastasis (suppresses); suppression of growth (promotes); invasion and metastasis (promotes)
Homologues: Orthologues: chimpanzee SETBP1 (99% identical), macaque SETBP1 (99% identical), dog SETBP1 (95% identical), pig SETBP1 (93% identical), rabbit SETBP1 (93% identical), guinea pig SETBP1 (91% identical), rat Setbp1 (90% identical), mouse Setbp1 (90% identical), tropical clawed frog setbp1 (64% identical), zebrafish setbp1 (42% identical), Drosophila melanogaster ash1 (8% identical), Caenorhabditis elegans met-1 (5% identical), and 16 more. Paralogues in human: ASH1L (29% identical), KMT2C (10% identical), KMT2D (10% identical), KMT2A (10% identical), KMT2B (8% identical), NSD1 (8% identical), NSD3 (7% identical), SETD1A (7% identical), SETD1B (7% identical), NSD2 (7% identical), EHMT1 (6% identical), SETD2 (5% identical), and 7 more.
Diseases named in the same sentence as SETBP1 in open-access papers:
SETBP1 is named in the same sentence as 124 diseases in open-access papers, as found by Europe PMC text mining. Sharing a sentence is not in itself a finding about the gene and the disease. The quoted sentences say what the papers report.
Schinzel-Giedion syndrome (31 papers, 2012 to 2026). "Schinzel-Giedion syndrome (SGS) is a very rare congenital disorder linked to de novo pathogenic variants in the SET Binding Protein 1 (SETBP1) gene." (PMID 42255817, 2026). "Schinzel-Giedion syndrome (SGS) is an ultra-rare Mendelian disorder caused by gain-of-function variants in the SETBP1 gene." (PMID 41757684, 2026). "Schinzel-Giedion Syndrome (SGS) is a rare neurodevelopmental disorder caused by pathogenic SETBP1 gain-of-function variants." (PMID 40859069, 2025). "Traditionally, SETBP1 mutations were recognized as the genetic cause of Schinzel-Giedion syndrome, a condition characterized by multiple severe congenital malformations." (PMID 41282480, 2025). "It is known that the SETBP1 gene mutation that usually causes Schinzel-Giedion midface retraction syndrome is a GOF mutation." (PMID 41282480, 2025). "Schinzel-Giedion syndrome (SGS) is a rare genetic disorder caused by heterozygous de novo mutations in the SETBP1 gene which is located on chromosome 18." (PMID 37892331, 2023). "On the other hand, a SETBP1 (V231L) mutation was found in Schinzel-Giedion Midface Retraction Syndrome with a mild effect, as reported by Illumina Clinical Services Laboratory (“VCV000159885.1-ClinVar-NCBI”, 2020)." (PMID 35328276, 2022). "Mutations on SETBP1 cause the Schinzel Giedion syndrome, individuals affected had a severe intellectual disability." (PMID 35057575, 2022). "Schinzel-Giedion syndrome (SGS) is a fatal developmental syndrome caused by mutations in the SETBP1 gene, inducing the accumulation of its protein product." (PMID 34193871, 2021). "SETBP1 mutations are associated with the Schinzel-Giedion syndrome (SGS), characterized by profound neurodevelopmental delay, typical facial features, and multiple congenital malformations (OMIM 269150)." (PMID 33391157, 2020). "SETBP1 gene located in the fragment which was responsible for Schinzel-Giedion midface retraction syndrome, and point mutation is the most common type." (PMID 28472932, 2017). "On the blood side of this signature were among others the PPP2R2B gene associated with SCA12, CAPNS2, which was recently found to play a beneficial role against polyglutamine toxicity, and SETBP1 which is associated with the Schinzel-Giedion syndrome." (PMID 27476530, 2016). "In a second benchmark, we reanalyzed a published case study of the Schinzel-Giedion syndrome and identified the causative gene, SETBP1, as the top-ranked gene, using default parameters." (PMID 23013645, 2012). "While the function of SETBP1 remains largely unknown, mutations in this gene are associated with Schinzel-Giedion syndrome, characterized by facial abnormalities, intellectual disability, congenital malformations, and HC." (PMID 38439105, 2024). "Next generation sequencing studies highlighted that SETBP1 variants known to cause the well-recognized Schinzel-Giedion syndrome (SGS) may be associated with a wide spectrum of clinical presentations." (PMID 33391157, 2020). "Schinzel-Giedion Syndrome (SGS) is a neurodevelopmental condition caused by SETBP1 gain-of-function variants." (PMID 40859069, 2025). "Germline de novo mutations in a hotspot of SETBP1 cause Schinzel-Giedion syndrome (SGS), a rare developmental disorder characterized by neurological alterations, malformations and increased cancer risk." (PMID 28346496, 2017). "Schinzel-Giedion syndrome (SGS; OMIM 269150) is a very rare congenital neurological disease caused by gain-of-function mutations in SETBP1 gene (SET-binding protein 1/SEB/MRD29) and has only 50 reported cases worldwide." (PMID 39108836, 2024). "Rare de novo heterozygous missense variants clustering in a specific degron region in SETBP1 that is important for its degradation cause Schinzel-Giedion syndrome (SGS, MIM #269150, OMIM 269150), a severe multi-system developmental disorder where most affected individuals do not survive infancy." (PMID 39580495, 2024).
Schinzel-Giedion syndrome (continued). "SETBP1, which encodes a SET binding protein, is a candidate for Schinzel-Giedion syndrome, which entails severe developmental delay and occasional epilepsy." (PMID 30405489, 2018). "Germline mutations in SETBP1 were first identified in children with Schinzel-Giedion syndrome (SGS), where SETBP1 mutations caused congenital disorder characterized by mental retardation, facial deformities and congenital anomalies." (PMID 28158286, 2017). "Germline variants cause the ultra-rare pediatric Schinzel Giedion Syndrome (SGS) and SETBP1 haploinsufficiency disorder (SETBP1-HD), characterized by severe multisystemic abnormalities with neurodegeneration or a less severe brain phenotype accompanied by hypotonia and strabismus, respectively." (PMID 38165902, 2024). "De novo gain-of-function variants of SETBP1 are associated with Schinzel-Giedion midface retraction syndrome (MIM #269150), while haploinsufficiency of SETBP1 caused by loss-of-function (LoF) variant or a heterozygous gene deletion is related to DD, autosomal dominant 29 (MIM #616078)." (PMID 34858471, 2021). "The SETBP1 gene duplication was in accordance with gain-of-function mechanism, and the child’s manifestations were similar with the phenotypes of Schinzel-Giedion midface retraction syndrome, Therefore, SETBP1 should be the main responsible gene for this patient." (PMID 28472932, 2017). "Recent studies demonstrated the involvement of SETBP1 germ line mutations in Schinzel-Giedion syndrome (SGS, OMIM269150) and SETBP1 Haploinsufficiency Disorder (SETBP1-HD, OMIM616078) and SETBP1 somatic mutations in several hematological malignancies." (PMID 37150818, 2023). "As often happens when a new gene involved in tumorigenesis is discovered, also in the case of SET binding protein 1 (SETBP1) gene, the first studies reported its involvement in the pathogenesis of a congenital disorder, called Schinzel-Giedion syndrome (SGS)." (PMID 28881700, 2017).
myeloid malignancies (26 papers, 2015 to 2026). "Somatic mutations of SETBP1 were associated with myeloid malignancies due to its gain-of-function or a dominant-negative effect." (PMID 37150818, 2023). "In the past, scholars focused on the relationship between SETBP1 mutations and tumors, especially myeloid malignancies and SETBP1 mutations was served as a biomarker for the diagnosis and poor prognosis of myeloid malignancies and the overlap syndrome." (PMID 37150818, 2023). "In a large study of 727 patients with various myeloid malignancies, SETBP1 mutations were found in 52 cases (7.2%)." (PMID 37150818, 2023). "Yet, of the remaining genes, FGFR3 was involved in proliferation and SETBP1 somatic mutations have been connected with myeloid malignancies." (PMID 34906245, 2021). "Clinical data revealed frequent coexistence of ASXL1 and SETBP1 mutations in myeloid neoplasms, and we previously demonstrated their cooperation to promote leukaemic transformation in mouse MDS/AML models." (PMID 30367089, 2018). "Intronic-PREX1 (20q13.13), a reported locus predisposing to MM was confirmed to have contribution to excess MGUS risk in interaction with SETBP1, a well-established candidate predisposing to myeloid malignancies." (PMID 30134812, 2018). "Several studies were focused on analysis of the prevalence, clinical and prognostic value of SETBP1 mutations in myeloid malignancies other than aCML." (PMID 28881700, 2017). "Taking into account the frequency of each mutation, we then compared the difference in degron-βTrCP1 interaction energy for SETBP1 mutations observed in SGS versus those observed in myeloid malignancies." (PMID 28346496, 2017). "In a large study of 1130 patients with myeloid neoplasms, SETBP1 mutations were found in 20/240 (9.3%) MDS/MPN-U patients." (PMID 29225884, 2017). "In this class of myeloid malignancies, SETBP1 mutations were observed in about 4-7% of patients when the analysis was performed with conventional sequencing methods; instead, when deep sequencing was employed, the mutation rate rose to 15%-19%." (PMID 28881700, 2017). "Through whole exome sequencing of DNA from 727 patients with various myeloid malignancies, recurrent mutations of SETBP1 were found in 52 cases (7.2%)." (PMID 29225884, 2017). "Somatic SETBP1 mutations observed in myeloid malignancies have been shown to have a gain-of-function effect on the SETBP1 protein, leading to decreased binding of the βTrCP1 and increased protein levels." (PMID 28346496, 2017). "Reports by several groups confirmed that the SETBP1 mutation is an important event in various classes of myeloid malignancies including CMML, CNL (Chronic Neutrophilic Leukemia), JMML, MDS, MDS/MPN (Myelodysplastic/Myeloproliferative neoplasms), and AML." (PMID 28881700, 2017). "High levels of MYB mRNA were also detected in 2 out of 4 human myeloid neoplasms with SETBP1 missense mutations." (PMID 27863435, 2016). "Similar to what was found in aCML, a different group identified recurrent somatic mutations in SETBP1 by whole-exome sequencing of individuals with various myeloid malignancies." (PMID 25763353, 2015). "Furthermore, SETBP1 mutations have been found to be involved in serval cancers, including myeloid neoplasms, lung cancer and colorectal cancer." (PMID 35898891, 2022). "Interestingly, shortly after the identification of germline de novo mutations in SETBP1 as the cause of SGS, overlapping somatic mutations in SETBP1 were reported in several types of myeloid malignancies." (PMID 28346496, 2017). "In therapy-related myeloid neoplasms (t-MN) only 3% of patients presented SETBP1 mutations." (PMID 28881700, 2017).
myeloid malignancies (continued). "Gaining an understanding of the specific cellular functions and related pathways of both the wild-type and mutant SETBP1 proteins will be crucial to identify new targets for therapeutic treatment and so improve outcomes for patients with myeloid malignancies who carry SETBP1 mutations." (PMID 28881700, 2017). "SETBP1 missense mutations have been frequently identified in multiple myeloid neoplasms; however, their oncogenic potential remains unclear." (PMID 27863435, 2016). "It remains unclear, however, how SETBP1 mutations may contribute to the development and progression of these myeloid neoplasms." (PMID 27863435, 2016). "SETBP1 missense mutations have been identified frequently during disease progression in various myeloid neoplasms; however, it is unclear whether these mutations are potent oncogenic driver mutations for the leukemic transformation of these diseases." (PMID 27863435, 2016). "The association of SETBP1 missense mutations with disease progression in myeloid neoplasms suggests that the mutations could be responsible for driving leukemic transformation in these diseases." (PMID 27863435, 2016). "Since the occurrence of SETBP1 mutations has been associated with disease progression in myeloid neoplasms, the leukemogenic capability of wild-type Setbp1 suggest that these mutations could be responsible for driving leukemic transformation of these diseases." (PMID 27863435, 2016). "SETBP1 germline mutations have been described in Schinzel–Giedion syndrome, a rare congenital disorder characterized by aberrant bone formation and predisposition to myeloid malignancies." (PMID 25763353, 2015). "Isolated isochromosome 17q, i(17q), accounts for less than 1% of myeloid neoplasms, including AML, MDS, and myeloproliferative neoplasms (MPN), and frequently harbors mutations in SETBP1, ASXL1, SRSF2, and NRAS." (PMID 41148513, 2026). "CNL can also arise from different myeloid neoplasms; a recent case report showed a patient who was diagnosed with MDS with U2AF1 and SETBP1 mutations who, 3 years later, developed CNL and acquired CSF3R and ASXL1 mutations." (PMID 39858009, 2025). "Despite evidence that SETBP1 confers worse prognosis in myeloid malignancies in general and aCML specifically, its impact has not been found deleterious in all studies." (PMID 35844680, 2021). "Activating mutations of the SET-binding protein 1 gene (SETBP1) and the overexpression of wild-type SETDB1 are associated with aggressive diseases and poor outcomes in myeloid neoplasms." (PMID 33768008, 2021). "Missense mutations of SETBP1 have been shown to increase the stability of the SETBP1 protein and result in its subsequent over expression in many myeloid neoplasms." (PMID 32457837, 2020). "We also observed a high frequency of ASXL1, SETBP1 and SRSF2 mutations in myeloid neoplasms associated with i(17q)." (PMID 26883102, 2016). "Although this association was lost in multivariate analysis, somatic mutations in the SETBP1 gene have been reported to be associated with myeloid malignancies including MDS, suggesting the potential implication of the SETBP1 mutation on HMT response." (PMID 27419369, 2016). "Recently, recurrent mutations in SETBP1, frequently targeting the SKI-homologous domain, have been identified in several types of myeloid malignancies, including chronic and acute myeloid leukemias (25 and refs. therein)." (PMID 26202160, 2015). "SETBP1 overexpression was associated with SGS and myeloid malignancies." (PMID 37150818, 2023).
myeloid malignancies (continued). "However, the clustering of all germline SETBP1 mutations identified in SGS to a single region and their overlap with the somatic events identified in myeloid malignancies support a gain-of-function effect on the SETBP1 protein." (PMID 28346496, 2017). "Interestingly, however, the list also includes SETBP1, a TF which has been reported to be oncogenic in myeloid neoplasms, highlighting the need to explore a potential tumour suppressive role of this TF in the context of epithelial cancer." (PMID 27562343, 2016). "Identification of Myb as a critical target of wild-type and mutant Setbp1 in our study suggest that inhibition of MYB could be a potential strategy for treating myeloid neoplasms with SETBP1 activation." (PMID 27863435, 2016). "Beyond that, a previous study showed that a single SETBP1 variant could be associated with a worse prognosis in myeloid neoplasms, regardless of the variant classification as VUS." (PMID 40725152, 2025). "In the past decade, SETBP1 has attracted a lot of interest on that the same gene with different type or level (germline or somatic) of variants could provoke different pathologic consequences such as Schinzel-Giedon syndrome, SETBP1 Haploinsufficiency Disorder (SETBP1-HD) and myeloid malignancies." (PMID 37150818, 2023). "Furthermore, the finding of interplay between MYB and mutant or wild type SETBP1 suggests that MYB inhibition could be a promising approach for treating myeloid neoplasms with SETBP1 activation." (PMID 28881700, 2017). "Furthermore, our results highlight that, despite the identification of overlapping SETBP1 mutations in SGS and myeloid malignancies, the mutation spectrum is significantly different in both conditions with functionally weaker mutations appearing predominantly as germline mutations in SGS." (PMID 28346496, 2017). "Furthermore, the sequential analysis of serial samples at multiple time points of the disease course, in two different series of patients with myeloid malignancies, showed that SETBP1 mutations were absent at the time of initial presentation while increasing in allele frequencies by time." (PMID 25763353, 2015). "As SETBP1 has a lower prevalence in other MDS/MPN except CMML or CNL, and ETNK1 is only otherwise seen in CMML and systemic mastocytosis, these genetic markers can be useful to distinguish aCML from other myeloid neoplasms." (PMID 35844680, 2021).